FBXW7 (F-box and WD repeat domain containing 7)
Diseases named in the same sentence as FBXW7 in open-access papers (continued):
Sharing a sentence is not in itself a finding about the gene and the disease.
gastric cancer (continued). "FBXW7 can target the degradation of MCL1,cyclin E,Notch,c-Jun and c-Myc, cancer genes related to the proliferation and regulation of gastric cancer cells." (PMID 28464881, 2017). "Similarly, in gastric cancer, ZC3H15 downregulates FBXW7 transcription, leading to increased c-Myc stability." (PMID 41513632, 2026). "The lncRNA BDNF-AS/WDR5/FBXW7 axis modulates ferroptosis in gastric cancer by impacting the ubiquitination of voltage-dependent anion channel 3 (VDAC3), thereby mediating peritoneal metastasis of gastric cancer." (PMID 39827195, 2025). "In addition, ubiquitin ligase FBXW7 has been shown to mediate the phosphorylation-dependent ubiquitination and degradation of GFI1 in gastric cancer cells." (PMID 34351909, 2021). "Since c-Myc degradation is also regulated by F-box/WD repeat-containing protein 7 (FBXW7), a widely studied F-box member with known tumor suppressor functions, we determined the correlation between FBXW5 and FBXW7 expressions in gastric cancer, both in-vivo and in-vitro." (PMID 31213005, 2019). "FBXW7 regulates expression of various oncoproteins, but the specific targets and related pathways are not clear in gastric cancer." (PMID 28464881, 2017). "However, in the gastric cancer development, miR-223 acts as an oncogene to promote cell invasion and migration via affecting expressions of EPB41L3 and FBXW7/hCdc4 genes." (PMID 26055874, 2015). "In conclusion, FBXW7 and MYC mRNA may play a role in aggressive biologic behavior of gastric cancer cells and may be a useful indicator of poor prognosis." (PMID 24053468, 2013). "Importantly, our date indicates that Fbxw7 positive expression is significantly correlated with a better 5-year patient survival for all HCC patients, which is consistent with the previous studies on gastric cancer, colorectal cancer, glioma and melanoma." (PMID 24884509, 2014).
colorectal cancer (97 papers, 2010 to 2026). A primary or metastatic malignant neoplasm that affects the colon or rectum. "Loss of FBXW7 promotes tumor progression by enhancing cell proliferation, invasion, and poor prognosis in colorectal cancer, acting as a tumor suppressor." (PMID 41373479, 2025). "FBXW7 loss-of-function mutations are frequently found in patients with colorectal cancer (CRC) and were found associated with the development of resistance to OXPT." (PMID 41174352, 2025). "ARID1A and FBXW7 are well-established tumor suppressors and are found mutated at similar frequencies in sporadic- and colitis-associated colorectal cancers." (PMID 32697969, 2020). "FBXW7 acts as an important tumor suppressor, and mutations in the FBXW7 gene have been found in ovarian, lymphoma, and colorectal cancers." (PMID 33042830, 2020). "We aimed to identify the mechanism underlying colorectal cancer (CRC) chemoresistance focusing on the cell cycle mediator F-Box/WD repeat domain-containing 7 (FBXW7)." (PMID 31067777, 2019). "FBXW7 has also consistently been identified as one of the most commonly mutated genes in colorectal cancer, being observed in 6 to 10% of all cases." (PMID 30458818, 2018). "FBXW7 functions as a ubiquitin ligase tagging multiple dominant oncogenic proteins and commonly mutates in colorectal cancer." (PMID 28424412, 2017). "FBXW7 encodes the substrate recognition component of a ubiquitin ligase that degrades targets such as Notch1, c-Jun, c-Myc and cyclin E. FBXW7 mutations occur in several tumour types, including colorectal cancers." (PMID 23676439, 2014). "In further support of this model, we found that overexpression of wild-type FBXW7 causes TGIF1 levels to reduce significantly in colorectal cancer cell lines that carry propellor tip mutations (LOVO, heterozygous R505C and SW1463, heterozygous R479Q)." (PMID 23676439, 2014). "The ubiquitin ligases CBL and SKP2 were identified as candidate oncogenes, while the ubiquitin ligase FBXW7 is a bona fide tumor suppressor that is mutated frequently in breast and colorectal cancers." (PMID 24874471, 2014). "And DEK expressions in epithelial cells are correlated with FBXW7 mutations in human colorectal cancer." (PMID 23902796, 2013). "Although mutations in Fbxw7/hCdc4 are frequent events in diverse tumor types, including endometrial carcinomas, cholangiocarcinomas, colorectal cancer and T-cell acute lymphoblastic leukemia, mutations are uncommon or absent in other malignancies." (PMID 21122106, 2010). "FBXW7 is a tumor suppressor gene that regulates metabolism and is associated with the onset and progression of colorectal cancer (CRC)), however, the precise mechanism whereby FBXW7 participates in the metabolic reprogramming of CRC remains unclear." (PMID 39823500, 2025). "In a comprehensive analysis of multiple data sets on colorectal cancer, it was also verified that mutations in FBXW7 mediated poor prognosis in colorectal cancer, which is consistent with the close association of FBXW7 mutations with colorectal cancer mentioned previously." (PMID 35346215, 2022). "Therefore, the loss of FBXW7 function results in accumulation of its substrates, which leads to oncogenesis and progression of multiple cancers including colorectal cancers." (PMID 30458818, 2018). "FBXW7 mutations occur in a variety of human cancers including colorectal cancer (CRC)." (PMID 25860929, 2015). "For colorectal cancer, we were able to analyze the effect of mutation-CNV co-occurrence on patient prognosis for three genes, namely APC, FBXW7, and PIK3CA." (PMID 41415395, 2025).
colorectal cancer (continued). "The miR-223/FBXW7 pathway regulates doxorubicin sensitivity through epithelial-mesenchymal transition in colorectal cancer cells, with miR-223 overexpression decreasing sensitivity." (PMID 40650042, 2025). "Among previously not reported associations with overall survival were mutations in GATA3 and FANCE genes in colorectal cancer, mutations in gene PTPN11 in glioma, and mutations in RNF43, MSH6 and FBXW7 genes in endometrial cancer." (PMID 39277826, 2024). "This analysis comprehensively identified FBXW7 alterations in colorectal cancer patients and uncovered the molecular, clinicopathological, and immune-related patterns of FBXW7-altered CRC patients." (PMID 37064111, 2023). "FBXW7 can affect the multiplication and apoptosis of colorectal cancer cells through Notch and Akt/mTOR signaling pathways." (PMID 35965327, 2022). "MYC-regulated miRNA-92b and miR-92a have also been shown to inhibit FBXW7 expression in colorectal cancer cells." (PMID 35346215, 2022). "A separate study revealed that FBXW7 binds to CRY2 in colorectal cancer cells, potentially through a direct interaction between the degron motif of CRY2 and the narrow face of the WD40 domain of FBXW7." (PMID 36142478, 2022). "One study showed that PLK2 promoted colorectal cancer growth and inhibited apoptosis by targeting Fbxw7/Cyclin E." (PMID 35156101, 2021). "One study discovered that FAM83D knockdown regulates the biological behavior of colorectal cancer by inhibiting the FBXW7/Notch-1 signaling pathway." (PMID 34869310, 2021). "In colorectal cancer (CRC), FBXW7 loss confers resistance to oxaliplatin and cisplatin chemotherapeutic agents, while CRC cell lines harboring FBXW7 mutations or deletions are more sensitive to rapamycin treatment." (PMID 32907612, 2020). "Mechanistically, FAM83D suppression promoted colorectal cancer cell apoptosis, inhibited cell proliferation, cell migration, and invasion through inhibiting the FBXW7/Notch1 signal pathway." (PMID 33363204, 2020). "As an oncogenic miRNA, miR-92b-3p promotes carcinogenesis and metastasis by down-regulating F-box and WD-40 domain protein 7 (FBXW7/hCdc4) in colorectal cancer." (PMID 32256526, 2020). "In vitro studies showed that suppression of FBXW7 increased colorectal cancer cell proliferation by upregulating c-Myc and cyclin E." (PMID 30791487, 2019). "FBXW7 can ubiquitinate c-Myc and cyclin E, resulting in exit from the cell cycle and subsequently inhibit cell proliferation of colorectal cancer." (PMID 23826080, 2013). "The human genes SMC1, SMC3, NIPBL, STAG3, RNF20, FBXW7/CDC4, MRE11A, RAD54B and BLM have been found to be mutated in colorectal cancer, and together account for approximately 25% of the CIN mutational spectrum of this disease." (PMID 23382697, 2013). "Additionally, we observed that the low-expression group exhibited a high mutational load, with FBXW7, SOX9, AMER1, SMAD4, ARID1A, and B2M being the most frequently mutated genes in colorectal cancer." (PMID 40170839, 2025).
colorectal cancer (continued). "Additionally, rapamycin, which is an mTOR inhibitor, attenuates the EMT process and stem-like properties that are driven by FBXW7 loss, which indicates the pivotal role of the FBXW7/mTOR axis in EMT regulation in colorectal cancer." (PMID 30999935, 2019). "FBXW7 mRNA expression is reported to be significantly reduced in colorectal cancer (CRC)." (PMID 30086763, 2018). "Although FBXW7 mutations are found in 14.3% of colorectal cancer, no one clinical, pathological or demographic feature is representative of the patients with FBXW7 mutations." (PMID 30086763, 2018). "Thus, DYRK2/FBXW7 axis modulates Paclitaxel sensitivity in colorectal cancer cell lines." (PMID 36934104, 2023). "Mutations in FBXW7 and CTNNB1 were associated with high-grade disease, the latter suggesting that activation of the Wnt pathway through CTNNB1 rather than APC mutation might predispose to poorly differentiated colorectal cancers." (PMID 30042065, 2018). "Circ_RNF13 contributes to the stabilization of TRIM24 by suppressing F-box and WD repeat domain containing 7 (FBXW7)-mediated TRIM24 degradation, thereby enhancing chemosensitivity in colorectal cancer." (PMID 39160596, 2024). "Activating the Wnt/β-catenin signaling pathway and inhibiting mitochondrial apoptosis by directly inhibiting FBXW7 and MOAP1 are helpful to the resistance of EMT and chemotherapy drugs in colorectal cancer." (PMID 38188683, 2023). "FBXW7 is an antagonist to the β-catenin of the WNT signaling, and exosomal miR-19b has been reported to target and suppress FBXW7 expression in colorectal cancer by enhancing its stemness and promoting radioresistance." (PMID 36674525, 2023). "miR-223 affects the proliferation and apoptosis of colorectal cancer cells via activation of the NOTCH and AKT/mTOR pathways; and inhibits FBXW7 in oesophageal squamous cell carcinoma." (PMID 35346215, 2022). "The E3-ubiquitin ligase FBXW7 targets multiple substrates such as C-JUN, C-MYC, and NOTCH1; it works as a tumor suppressor for colorectal cancer by inhibiting Notch signal." (PMID 36147468, 2022). "Recently, we reported that IPA inhibits colorectal cancer (CRC) proliferation in vitro and in vivo by increasing the expression of the tumor suppressor FBXW7 and, in turn, regulating the FBXW7/SREBP/FDPS axis, corroborating with previous studies." (PMID 35559231, 2022). "The ubiquitin ligase F-box and WD repeat domain-containing 7 (FBXW7) plays an anti-cancer role in many cancers, such as HCC, colorectal cancer and gastric cancer." (PMID 32366840, 2020). "Zhan et al24 found that FBXW7, an E3 ligase, negatively regulates the expression of ENO1 by interacting with ENO1 and increasing its proteasomal degradation in colorectal cancer." (PMID 31957179, 2020). "Circ-FBXW7 controls the progression of CRC through NEK2, mTOR, and PTEN signaling pathways and its overexpression inhibits colorectal cancer cell migration and invasion, suggesting the potential therapeutic target for CRC treatment." (PMID 31519156, 2019). "For example, two groups reported that depletion of FBXW7 significantly promotes EMT and the generation of CSCs in colorectal cancer and cholangiocarcinoma cells." (PMID 30999935, 2019). "In colorectal cancer, FAM83D knockdown up-regulated the protein expression level of FBXW7, but diminished the Notch1 protein expression level." (PMID 30910840, 2019).
colorectal cancer (continued). "However, the role of circ-FBXW7 in colorectal cancer (CRC) remains unclear." (PMID 31519156, 2019). "Collectively, these pieces of evidence suggest that FAM83D may be involved in the FBXW7/NOTCH1 degradation pathway and therefore, may be explored as a molecular target for colorectal cancer diagnosis and treatment." (PMID 33822486, 2021). "Furthermore, shRNA-mediated 75% knockdown of FBXW7 mRNA in colorectal cancer lines with propellor tip mutations produced no significant increase in TGIF1 levels, suggesting that the monoallelic mutation produced a strong functional effect that could not readily be enhanced in the system used." (PMID 23676439, 2014).
pancreatic cancer (59 papers, 2014 to 2025). "Downregulation of FBXW7 has been observed in breast, gastric and pancreatic cancers, where its low expression associates with unfavorable prognosis." (PMID 39213172, 2024). "Mechanistic studies have shown that FBXW7 loss in mice depends on Yap accumulation to drive pancreatic tumor formation." (PMID 39749199, 2024). "F-box and WD repeat domain-containing 7 (FBW7) is one of the most commonly mutated genes in human cancers that is expressed at low levels in pancreatic cancer." (PMID 34503532, 2021). "It has been reported that low FBXW7 expression is associated with tumor progression in a diverse array of malignancies including breast, endometrial, ovarian, and pancreatic cancers as well as T-cell acute lymphoblastic leukemia." (PMID 28464881, 2017). "In pancreatic cancer, a recent report showed that Ras/Raf/MEK/ERK activation induced by KRAS mutations, which are frequently observed in pancreatic cancer, plays important roles in reducing FBXW7 expression." (PMID 29348852, 2017). "The present study is the first report demonstrating an association between FBXW7 expression and chemosensitivity in pancreatic cancer." (PMID 29348852, 2017). "Here, we demonstrated that low FBXW7 expression in pancreatic cancer tissue was associated with cancer progression and was an independent factor predicting poor prognosis." (PMID 29348852, 2017). "Loss-of-function mutations of Fbxw7 led to the accumulation of Cyclin E and played a key role in the progression of human pancreatic cancer." (PMID 24884509, 2014). "Additionally, the oncogenic KRAS mutation-suppressed pancreatic tumor suppressor F-box and WD repeat domain-containing 7 (FBW7) suppressed glycolysis in pancreatic cancer cells and improved the effectiveness of gemcitabine in xenograft models." (PMID 36831413, 2023). "In addition, F-box and WD repeat domain-containing 7 (FBW7), a pancreatic tumor suppressor inhibited by oncogenic KRAS mutation, inhibited glycolysis in pancreatic cancer cells and enhanced the efficacy of gemcitabine in xenograft models as well." (PMID 32122374, 2020). "By suppressing Nur77 in pancreatic cancer cells, FBW7 (F-box and WD repeat domain-containing 7) reduces the expression of stearoyl-CoA desaturase (SCD1) and enhances ferroptosis." (PMID 38789431, 2024). "The epigenetic regulator protein arginine methyltransferase 5 (PRMT5) stabilizes c-Myc levels in pancreatic cancer cells by downregulating FBXW7, promoting tumor cell proliferation." (PMID 39749199, 2024). "This occurs because the ERK pathway degrades FBXW7 in a phosphorylation-dependent manner, and pancreatic cancer cells with defective FBXW7 phosphorylation sites exhibit oncogenic resistance to ERK pathway activation." (PMID 39749199, 2024). "Genistein was found to affect the biological behavior of pancreatic cancer cells by increasing FBXW7 expression through the downregulation of miR-223." (PMID 38027013, 2023). "In pancreatic cancer, the tumor suppressor FBW7 (F-box and WD Repeat Domain-Containing 7) exerts its antitumor effects by controlling glucose metabolism and oxygen consumption in a TXNIP-dependent manner." (PMID 37794178, 2023). "USP5 promotes tumorigenesis of pancreatic cancer cells by stabilising the FoxM1 protein, which is a substrate of FBXW7." (PMID 33658627, 2021). "FBXW7 also influences the proliferation and survival of pancreatic cancer cells through the Ras/Raf/MEK/ERK signalling cascade." (PMID 32394588, 2020). "In pancreatic ductal adenocarcinoma, miR-223 was reported to promote pancreatic cancer cell growth and invasion by targeting FBXW7." (PMID 32577098, 2020). "Aside from that, miR-223-3p involved in the regulation of cisplatin-resistance of pancreatic cancer, osteosarcoma and GC, especially, miR-223-3p promoted cisplatin resistance of GC cells via targeting F-box and WD repeat domain containing 7 (FBXW7)." (PMID 32516127, 2020).